TNF (tumor necrosis factor)
Diseases named in the same sentence as TNF in open-access papers (continued):
Sharing a sentence is not in itself a finding about the gene and the disease.
infection (continued). "In addition, infection of BEAS2B cells (human lung epithelial cell line) with hRSV kept them from inhibiting the secretion of pro-inflammatory cytokines by monocytes, such as TNFα." (PMID 29230219, 2017). "Interestingly, p65 and ERK1/2 phosphorylation decrements were related to the inhibitory ability of these pathotypes, since co-stimulation experiments showed that EPEC/EHEC prevents TNF-α-induced p65 phosphorylation and EGF-induced ERK1/2 phosphorylation post-infection." (PMID 27774437, 2016). "In contrast, the optimal treatment window for anti-TNF-α agents was between 6 hours and 8 hours after infection, which may explain why anti-TNF-α treatment did not effectively improve survival for patients in some clinical studies." (PMID 27556404, 2016). "In this study, significant increase in the levels of pro-inflammatory type 1 (TNF-α, IFN-γ, IL-6, IL-1β), pro-inflammatory type 2 (IL-33) and anti-inflammatory type 2 cytokines was observed in unimmunized mice after bacterial challenge indicating the spread of infection." (PMID 26904021, 2016). "Ca2+ elevation, especially due to store-operated Ca2+ entry (SOCE), is also involved in TNF-α release from microglial cells under chronic purinergic stimulation; however, the mechanism of Ca2+ signaling in regulating TNF-α production under pathogen infection has not been clearly demonstrated." (PMID 27472555, 2016). "Interestingly, we found that the expression of Kepi doubles in Tnfrsf1a/1b−/−mice during infection (not shown), suggesting the presence of a negative feedback loop between Kepi and TNFα signaling." (PMID 27663205, 2016). "However, pretreatment of macrophages with IFN-γ or TNF-α did not enhance MET formation by infection with M. mass R or CIP." (PMID 27191593, 2016). "Infection by Gram-negative bacteria and their cell wall component, lipopolysaccharide (LPS), has been shown to inhibit production of prolactin in the pituitary gland, mediated by TNF." (PMID 27119014, 2016). "Irrespective of the infection site, the number of early recruited macrophages is comparable in both tnfr morphants and WT embryos at 2 hpi, implying that TNF signaling is not required for the early trafficking of macrophages, consistent with previous studies with M. marinum." (PMID 27806130, 2016). "Infection with CIV alone, Sp alone or coinfection stimulated a significantly higher release of cytokines, such as interferon-gamma (IFN)-γ, interleukin 6 (IL)-6, tumor necrosis factor (TNF-α) and lymphotactin (Lptn), than was observed in the mock-infected group (PBS)." (PMID 27259293, 2016). "Similarly, TNF-α secretion was also analogous between the two intracellular strains with no response at 0.5 h of infection but at 1, 2, and 4 h the responses ranging 0.12 and 0.22 ng/ml, without a statistical difference." (PMID 27774437, 2016). "The cloning and sequence analysis of hamster genes related to infection with L. donovani in this animal model was described, revealing a non-polarized immune response profile characterized by an increase in expression of IL-2, IL-12, IFN-ɣ, TNF, IL-10 and TGF-β genes." (PMID 27350537, 2016). "The total lack of TNF-positive cells in macrophage-depleted Tg(tnfα:eGFP-F) larvae, generated after lipo-clodronate injection, confirmed macrophages as the primary source of TNF in response to Mabs infection." (PMID 27806130, 2016). "The fact that FTY720 enhanced the frequency of cells producing both TNFα and IFNγ, in MAITs, CD8 T cells, and CD4 T cells, while declining that of TNFα single-producer cells in CD4 T cells suggested beneficial effects of FTY720 on the host defense against infection." (PMID 27536542, 2016). "To investigate whether the NLRP7 inflammasome plays a role in the production of TNF-α and CCL3 besides IL-1β and IL-18, we silenced NLRP7 or ASC in THP-1 macrophages prior to infection, which significantly attenuated M. bovis-induced upregulation of TNF-α, CCL3 and IL-1β at the mRNA level." (PMID 27043315, 2016).
infection (continued). "Likewise, TNF-α levels, which were increased early in infection in mice, were (non-significantly) increased during the acute phase of infection in the patients." (PMID 27163257, 2016). "Retrospective analysis comparing responses to early infection (3 WPI) by non-vaccinates versus culture-negative vaccinates (n = 14) or culture-positive vaccinates (n = 5) revealed differential IFN-γ/TNF-α responses by Tcm cells to ESAT-6:CFP10 among the groups (P < 0.05)." (PMID 27799930, 2016). "The prevalence of past infection in RA patients, whether treated or nontreated with anti-TNF-α medicines, was similar, 15.8% and 13.8%, respectively." (PMID 27656302, 2016). "The levels of inflammatory cytokines and chemokines, i.e., IL-6, TNF-α, CCL3/MIP-1α, CXCL1/KC, and CXCL10/IP-10, which have been reported to contribute to lung pathology, also decreased in BALF from Mint3−/− mice compared to those from WT mice on day 4 after infection." (PMID 27883071, 2016). "Although peripheral inflammatory events including the circulation of high concentrations of the cytokines IFN-γ and TNF-α are already occurring one-week post infection, GS and GLAST transcripts are not significantly different than naïve levels and GLAST transcription remains unaltered." (PMID 27281462, 2016). "However, our experimental infection in chickens shows the two viruses exhibited no obvious differences in body weight loss, viral loads of tissues and swabs, and levels of IFN-γ and TNF-α." (PMID 27160077, 2016). "Interestingly, the set of data [EPO + hemopexin + total heme] correlated significantly to [TNF-α + IL-10 + IP-10 + MCP-1] during infection, and more specifically for the CM, and NCM groups, but not for MM patients." (PMID 27441662, 2016). "In our previous microRNA-mRNA array analysis, we have found that Bp infection elevates the levels of apoptotic inflammatory cytokines, in particular TNF-α, with the fold-change value of 74.94 at 24 hpi (hours post infection, compared to negative control), which was much more higher than that of Bt." (PMID 27894256, 2016). "While M. tuberculosis infected TNFα-deficient mice receiving no antibiotics developed a severe disease within 3 weeks, Isoniazid (INH) and Rifampicin (RIF) treated TNFα-deficient mice survived beyond 8 weeks post infection." (PMID 27853279, 2016). "Thus, in a model of infection and chemotherapy adequate to observe reactivation of M. tuberculosis infection in the complete absence of TNFα, there was no major effect of IL-17A neutralization." (PMID 27853279, 2016). "Additionally, PCV2 infection of PK-15 cells that were treated with SOCS3 siRNAs exhibited elevated levels of IL-6 and TNF-α, compared with control cells, thereby demonstrating that PCV2 activated SOCS3 to minimize these proinflammatory responses to promote a subclinical infection." (PMID 27581515, 2016). "However, this is not inconsistent with our result showing up-regulation of TNF-α expression at one wpi due to the previous observation of the mixed Th1/Th2 response at the early stage of infection." (PMID 27661612, 2016). "Regarding H1N1 and H3N2 infection, respectively, although the maximum value for TNFα and IκB ratio was also observed at 16 and 48 hpi, it remained always higher than that detected for H1N1 and H3N2, respectively, at 16 and 48 hpi, or for mock infection, during 16 and 48 hpi." (PMID 27042352, 2016). "However, non-TNFα-related mechanisms (e.g. through IL1β, TLR4 etc.)could still be able to control progress of the infection, and the net result is decreased pathogenicity." (PMID 27663205, 2016). "Therefore, to determine if neuron infection is TNF dependent, we investigated whether dissemination of M. tuberculosis to the CNS of TNF−/− mice resulted in bacilli infection of neurons." (PMID 26112704, 2015).
infection (continued). "Indeed, it has been shown that inactivated CVB4 can stimulate the production of IL-6, TNFα and IL-12 by monocytes, which suggests that a replicative infection of monocytes/macrophages by the virus is not mandatory for inducing inflammation." (PMID 26610550, 2015). "In addition, in TNF-deficient mice L. major-specific T cells displayed strong in vitro IFN-γ expression, but in vivo failed to achieve control of L. major as TNF-/- mice succumbed to the infection within 6–7 weeks." (PMID 26834705, 2015). "TNF-α release at the site of infection was not dependent upon the ability of the infecting isolate to produce active α-toxin since the wild-type C. septicum strain activated TNF-α release to approximately the same extent as the Δcsa, C86L and Δcsa(csa+) strains." (PMID 25675415, 2015). "If the cells became damaged early after infection, they may have not been able to produce significant amounts of TNFα afterwards." (PMID 29470790, 2015). "The κ-carrageenan could decrease the IL-6 and TNF-α mRNA levels but promote the IL-1β mRNA synthesis with or without SW731 infection." (PMID 25969984, 2015). "Interestingly, the levels of a number of Th1 (IFN-γ, TNF-α, GM-CSF) and Th2 (IL-5, IL-6) cytokines were significantly reduced following the PZQ+EDLF combined treatment as compared to infected untreated mice at the late stage of infection." (PMID 26191954, 2015). "In addition, in preliminary experiments we failed to reproduce these results using infection of polarized and TNF-treated HepG2 cells with LCMV (data not shown)." (PMID 25822203, 2015). "However, there was not even a tendency towards reduced TNFα levels after pretreatment with magnesium-derived particles plus infection." (PMID 29470790, 2015). "Conversely, 15 days after treatment of blood stage infection with chloroquine, splenocytes showed spontaneous in vitro expression of TNFα, IL2, IL6, IL10, and IL12, but not IFNγ, and stimulation with P. falciparum pRBC blocked the expression of all these cytokines." (PMID 25890318, 2015). "To determine whether TNF-α is required for protection against C. tropicalis in vivo, we treated WT mice with a soluble TNFR-blocking agent (etanercept), starting at day −1 and continuing every 2 d throughout the infection (continuous)." (PMID 26336150, 2015). "However, in the present study with two daily doses of ceftriaxone, anti-TNF-alpha treatment did not reactivate the infection." (PMID 25816291, 2015). "While TNFα-producing CD4+ T cells were not independently associated with future protection, the absence of cells producing this inflammatory cytokine was associated with the phenotype of asymptomatic infection." (PMID 24415936, 2014). "Taken together, these results suggest that direct non-productive RGH infection is regulated by the action of NFκB signaling at the time of infection and that the propensity to form a non-productive infection can be modulated by NFκB agonists (TNFα and PMA/Iono) and antagonists (BMS-345541)." (PMID 24502247, 2014). "Similar to TNFα treatment at the time of infection, treatment with TNFα four days post-infection was able to reactivate a large proportion of non-productive proviruses, as demonstrated by a decrease in the size of the ‘red’ population, and a corresponding increase in the number of ‘yellow’ cells." (PMID 24502247, 2014). "The remainder, IL 23, IL 10 and TNFα may be indirectly related or may represent a non-specific response to the stress of infection." (PMID 25391018, 2014). "At 48 h post-infection, the lower levels of IL-10 and IL-12 and trend for reduced TNF-α in CPEfat/fat mice may have been due to the non-significant trend for lower spleen CFUs." (PMID 25203099, 2014). "The reason why the existence of TNF-α did not activate the extrinsic pathway may be that TNF-α was induced only during a late stage of infection (24 h after infection)." (PMID 24923273, 2014). "TLR9-/- AMs infection with the ΔPscf mutant induced both TNFα and IL-6 but failed to induce IL-1β." (PMID 24595157, 2014).
infection (continued). "Interestingly, patients who had subsequent infections did not produce TNFα after an LPS challenge, but they did produce IL10 and showed lower levels of pro-inflammatory proteins in plasma than patients with UA." (PMID 24797663, 2014). "Thus, enhanced IL-2, IL-12, TNF-α and IFN-γ mRNA expression but downregulation of IL-10, most remarkable in cocktail vaccinated hamsters is chiefly responsible for strong Th1 biased immunity after infection." (PMID 25144181, 2014). "We found that the levels of proinflammatory cytokines, including IL-6, MCP-1, IL-1β, TNF-α, and IFN-γ, increased immediately after infection and peaked on day 3 postviral infection, before returning to their baseline levels about 7–10 days after infection in both mouse strains." (PMID 24676272, 2014). "The aim of this retrospective observational cohort study was to evaluate the impact of DMARDs, CS and the three TNFα antagonists licensed in Italy between 2001 and 2005, in mono or combination therapy, on non-serious and serious infections in RA and SpA patients." (PMID 24655394, 2014). "Furthermore, combining IL-1β or TNF-α with IFN-γ (100 ng/mL) reduced infection to control levels, similar to that of IFN-γ alone (data not shown)." (PMID 24259385, 2014). "This may be due to the reason that control of in vitro infection by MΦ is not solely due NO production but also by the milieu of cytokines and chemokines, specially IL-12 and TNF-α secreted by the parasitized APCs." (PMID 25144181, 2014). "Tumor necrosis factor-alpha was also notably absent from both studies despite previously published and unpublished data (Wiens, unpublished data) suggesting upregulation during infection." (PMID 25620978, 2014). "Lacz infection did not alter the adhesion molecules expression modulation induced by TNFα." (PMID 25329324, 2014). "Additionally, the deficiency of pandemic-like H5N1 whole virus vaccines to induce secretion of inflammatory cytokines (i.e. IL-6, TNF-α, and IFN-α) was unexpected, since the infection of humans with live H5N1 viruses was reported to be associated with hypercytokinemia." (PMID 25072749, 2014). "Besides a modest increase in TNF-α levels and increased peripheral blood neutrophil counts in CPEfat/fat mice, there were not differences in lung or serum cytokines after infection." (PMID 25203099, 2014). "These cells could phagocytose fungal cells, initiate antigen presentation, as well as secrete key cytokines such as tumor necrosis factor-α (TNF-α) and interleukin (IL)-12, chemokines and other molecules that initiate the inflammatory reaction and modulate the infection." (PMID 25372145, 2014). "When stimulated through the Fas pathway, HSV-2 infected macrophages do not only undergo apoptosis but may also up-regulate the production of TNF-α, CXCL9 and CXCL10 - chemo-attractants for activated T cells and NK cells necessary to eradicate local infection and inflammation." (PMID 23922974, 2013). "Similarly to the results observed with TNF-/- OT-I cells, we observed a significantly greater proportion and absolute number of TNFR2-/- OT-I cells compared to WT OT-I cells in the lung at day 12 post-infection." (PMID 23874808, 2013). "Additionally, no statistical difference was observed in TNF, IL-10 and IL-4 production in the organ under infection and STAg-pretreatment, despite TNF detection presented a trend to be lower in STAg-pretreated compared to PBS-pretreated mice." (PMID 24086456, 2013). "Thus, the vaccine-induced response generated by TB10.4 was very similar to the ESAT-6 induced response both in terms of magnitude and quality i.e. the proportion of IFN-γ+IL-2+TNF-α+ CD4 T cells and differed markedly from the infection promoted response to these antigens." (PMID 24349004, 2013).
infection (continued). "By contrast, at 7 days post infection, the levels of CCL2, CCL3, CXCL2, IFN-γ and the anti-inflammatory cytokine IL-10 were significantly lower in influenza A virus-infected Nox1−/y lung compared to WT control, whereas IL-β, IL-6, TNF-α, and GM-CSF were similar between the two strains of mice." (PMID 23577160, 2013). "The levels of IFN-γ and TNF-α were not significantly changed after infection with Ck/NL." (PMID 23874602, 2013). "Although the high virulence of JaTH160 is probably attributable to viral factors, we attempted to assess whether or not TNF-α might also contribute significantly to the pathogenicity observed following infection with JaTH160 virus." (PMID 23940775, 2013). "However, we did not observe increased mRNA expression of TNF-α in the spleen or bone marrow of infected hamsters at 5 and 8 wks post-infection compared to control hamsters." (PMID 23533629, 2013). "In addition, MC58 Nm isolated directly from the peritoneum and blood of mice 4 h post-infection exhibited TNF-α uptake, whereas ΔpglC/L mutant Nm did not in EM experiments." (PMID 24107297, 2013). "Moreover, we performed logistic regression and ROC analyses for post-operative IL-6 and TNF-α levels; however, they were not important predictors of infection (data not shown)." (PMID 23520452, 2013). "Expression levels of interleukin (IL)-4, IL-10, IL-13 and tumor necrosis factor (TNF)-α were significantly up-regulated while interferon (IFN)-α, IFN-β, IFN-γ, IL-1β,IL-2, IL-3, IL-15, IL-17F, IL-18 and colony-stimulating factor (CSF)-1 were markedly decreased in PBMCs at all stages of infection." (PMID 24358317, 2013). "Taken together, our data showed that the adjuvanted subunit and MVA strategies led to different T cell subset combinations pre and post infection and that TNF-α/IL-2 double producing but not IFN-γ single producing CD4 T cell subsets correlated with protection in the mouse TB model." (PMID 23977248, 2013). "In this study, the IL-10/TNF-alpha ratio in macrophages within this short time period may not be relevant to the outcome in mouse and human infection." (PMID 24130911, 2013). "In contrast to IFN-α, massive numbers of TNF-α-producing cells were present in lymph nodes at both day 14 and 56 post infection, regardless of TLR7 and TLR9 blockade, with 25 to 30% of all cells in the paracortex and parafollicular cortex expressing this cytokine." (PMID 23935491, 2013). "The risk of progressing to active disease after infection decreases with time after infection and is increased in the presence of certain medical conditions including HIV infection, silicosis, diabetes, renal replacement therapy, gastrectomy, smoking, underweight and TNF-alpha-blocker treatment." (PMID 24098794, 2013). "These IFNγ−IL-2+TNFα+ CD4 T cells may be an important target population for vaccination regimens, as these cells are induced upon infection, may have high proliferative potential, and may play a role in providing future effector cells during subsequent infections." (PMID 23526940, 2013). "Although this aberrant cytokine response is assumed to cause acute respiratory distress syndrome and death in mammals, H5 HPAIV infection was also lethal to mice lacking TNF and IL-1 receptors, and immunosuppressive treatment was not always an effective therapy for H5 HPAIV infection in mice." (PMID 23874602, 2013). "Following infection with N. caninum in cattle, CD4+ T lymphocytes are principal components of the Th1 response and produce pro-inflammatory Th1 type cytokines including IFN-γ, TNF-α and IL-12, which have an essential role in protective immunity against the parasite." (PMID 23876124, 2013). "However, its absence at 5 and 8 weeks post-infection suggest TNF-α is not involved in inhibiting erythropoiesis at these time points." (PMID 23533629, 2013).